RYR1 (ryanodine receptor 1)
Diseases named in the same sentence as RYR1 in open-access papers (continued):
Sharing a sentence is not in itself a finding about the gene and the disease.
malignant hyperthermia syndrome (3 papers, 2014 to 2023). "In Pietrain pigs (PiPP), mutations in ryanodine receptor 1 (RYR1) are associated with susceptibility to malignant hyperthermia syndrome (MHS) and reduced meat quality (pale, soft, exudative)." (PMID 31195974, 2019). "Chronically elevated [Ca2+]rest is a common feature of skeletal muscle cells expressing RyR1 mutations linked to MHS (malignant hyperthermia syndrome)." (PMID 24635445, 2014). "Moreover, within the Pietrain breed, we considered animals of both homozygous genotypes at the RYR1 g.1843C > T SNP that causes malignant hyperthermia syndrome (MHS) in pigs." (PMID 31195974, 2019). "These experiments describe the effects of local heating on calcium release from intracellular stores through IP3 receptors in Hela cells as well as calcium release through RYR1 Malignant Hyperthermia Syndrome mutants in human embryonic kidney 293 cells correspondingly." (PMID 37236978, 2023).
metabolic myopathies (3 papers, 2015 to 2022). "Currently, myopathies with mutations in RyR1 are not considered metabolic myopathies, even though RyR1-S2844D mice with an intracellular calcium leak and muscle weakness exhibit decreased levels of mitochondrial activity and metabolic enzymes." (PMID 25564733, 2015).
Minicore myopathy (3 papers, 2013 to 2021). Multiple small zones of sarcomeric disorganization and lack of oxidative activity (known as minicores) in muscle fibers. "In some contexts (e.g. minicore myopathy) it can be used to help distinguish patients with RYR1 mutations from other genetic subtypes." (PMID 23919265, 2013).
myositis (3 papers, 2019 to 2023). "In one patient, the NGS panel revealed RYR1 pathogenic variant causing hyperthermia maligna; this child had a previous history of myositis." (PMID 37462800, 2023). "Nearly one-fifth of a cohort of subjects who had severe statin myositis had rare variants within genes for RyR1 and the pore-forming subunit of the L-type Ca2+ channel." (PMID 31468006, 2019). "The first had a CPK peak value (17,690 UI/L) significantly higher than the median values of the cohort with a normalization time significantly longer (8 days) than the others; the second, with RYR1 mutation and COVID infection, had a history of two previous episodes of myositis." (PMID 37462800, 2023).
Myotonia (3 papers, 2013 to 2019). An involuntary and painless delay in the relaxation of skeletal muscle following contraction or electrical stimulation. "The combined effect of increased ECC activity coupled with myotonia, due to mis-splicing of a chloride channel, and altered Ca2+ homeostasis (RyR1 and SERCA1 mis-splicing) may lead to a chronic Ca2+ overload already observed in DM1 myotubes." (PMID 24705164, 2013).
sarcopenia (3 papers, 2013 to 2025). Progressive decline in muscle mass due to aging which results in decreased functional capacity of muscles. "Defective SR Ca2+ release and maladaptive modifications of the RyR1 have been implicated in age-dependent muscle weaknesses such as sarcopenia." (PMID 36358481, 2022). "In this context, RyR1 S-nitrosylation strengthens aging-induced sarcopenia, as uncontrolled Ca2+ release by RyR1 from the sarcoplasmic reticulum (SR) causes activation of Ca2+-dependent proteases, the calpains." (PMID 23538841, 2013).
Strabismus (3 papers, 2021 to 2025). A misalignment of the eyes so that the visual axes deviate from bifoveal fixation. "Disturbed vision due to strabismus or diplopia was reported in 7 patients (15%), mainly in RYR1 and MTM1 patients." (PMID 34463354, 2021).
thymoma (3 papers, 2023 to 2025). A neoplasm arising from the epithelial cells of the thymus. "Myoid cells and TECs also express other muscle antigens, including RYR1 and TTN, which are two autoantigens in thymoma-associated MG." (PMID 36979710, 2023). "Anti-RYR1 antibodies were detected in available sera from 13 of 17 MG patients with thymoma, including 6 out of 6 patients with type A/AB, 4 out of 5 patients with type B1/B2, and 3 out of 6 patients with type B3/B3 mixed thymoma." (PMID 36979710, 2023). "In MG thymomas, RYR1 down-regulation mainly involved type A/AB tumor subset compared to the corresponding subset in non-MG tumors." (PMID 36979710, 2023). "Accordingly, we found a significant RYR3 overexpression in MG, particularly of type B3/B3 mixed, along with A/AB, compared to non-MG thymomas, hyperplastic MG, and control thymuses, thus suggesting an association between RYR3 overexpression and autoreactivity to RYR1 developing inside the thymoma." (PMID 36979710, 2023). "Most patients were positive for AChR Abs associated with titin Abs, RyR1 Abs associated with thymomas, and negative for MSAs." (PMID 37781409, 2023). "Several early studies have searched for evidence of an altered expression of the AChR-α subunit in MG thymuses; RYR1 and TTN expression was also widely investigated in MG thymomas." (PMID 36979710, 2023). "The small sample size of the histological tumor subgroups did not allow us to draw definitive conclusions on the relationship between muscle/muscle-like autoantigen expression and autoantibody (anti-RYR1 and anti-TTN) profile in thymoma patients." (PMID 36979710, 2023). "RYR1 and TTN epitopes, along with costimulatory molecules, were detected in neoplastic thymoma cells, suggesting a primary autosensitization to these autoantigens in the neoplastic thymic tissue." (PMID 36979710, 2023). "We found that CHRNA1 (AChR-α subunit) and AIRE (autoimmune regulator) genes were expressed at lower levels in hyperplastic and thymoma MG compared to the control thymuses, and that the RYR1 and TTN levels were decreased in MG versus the non-MG thymomas." (PMID 36979710, 2023). "In both MG and non-MG thymomas, type A/AB tumors showed higher RYR1 mRNA levels than the histological B subtypes." (PMID 36979710, 2023). "Anti-AChR, anti-RYR1, and anti-TTN antibodies were tested in 13 available sera from non-MG thymoma patients, including 7 patients with type A/AB, 5 patients with type B1/B2, and 1 patient with type B3/B3 mixed thymoma." (PMID 36979710, 2023). "The neuronal ryanodine receptor, RYR3, sharing homology with muscular RYR1, was found to be up-regulated in MG compared to non-MG thymomas by Radovich and colleagues, with the highest up-regulation being observed in the B1/B2/B3 subset." (PMID 36979710, 2023). "To further address the question whether the intra-thymic expression of muscle autoantigens is altered in AChR-MG patients, we searched for possible changes in the CHRNA1, RYR1, and TTN expression levels, in relationship with AIRE expression, in hyperplastic MG thymuses and MG thymomas." (PMID 36979710, 2023). "RYR1 expression was significantly reduced in hyperplastic and thymoma thymuses from corticosteroid-naïve, but not corticosteroid-treated, MG patients compared to control thymuses and non-MG thymomas, respectively." (PMID 36979710, 2023). "Similarly to CHRNA1, genes encoding for the two thymoma-associated autoantigens RYR1 and TTN were expressed at lower levels in MG compared to non-MG thymomas, with RYR1 being mainly down-regulated in the MG A/AB subset, and TTN in the MG A/AB and B3/B3 mixed subset." (PMID 36979710, 2023). "Transcriptional levels of CHRNA1, RYR1, and TTN autoantigen genes were assessed in hyperplastic and thymoma thymuses of MG patients, non-MG thymomas, and normal thymuses using real-time PCR." (PMID 36979710, 2023).
thymoma (continued). "As observed for RYR1, the type A/AB subset showed lower TTN mRNA levels in MG compared to non-MG thymomas, but the differences were not statistically significant." (PMID 36979710, 2023). "One patient with type A/AB thymoma, who was negative for anti-AChR antibodies, was positive for both anti-RYR1 and anti-TTN antibodies; the remaining non-MG thymoma patients were negative for autoantibodies." (PMID 36979710, 2023). "RYR1 was also down-regulated in thymomas from anti-RYR1 antibody-positive MG patients with B3/B3 mixed thymomas, who showed a down-regulation of AIRE and an up-regulation of RYR3, compared to thymomas of the same type in seronegative non-MG patients." (PMID 36979710, 2023).
ventricular tachycardia (3 papers, 2013 to 2024). A disorder characterized by an electrocardiographic finding of three or more consecutive complexes of ventricular origin with a rate greater than a certain threshold (100 or 120 beats per minute are commonly used). "Mutations in RyR1 and RyR2 lead to life-threatening malignant hyperthermia episodes and ventricular tachycardia, respectively." (PMID 36311249, 2022). "For example, mutations of RyR1 C-terminal region (3916–4973) are often observed in CCD, and mutations of RyR2 C-terminal region (3778–4959) cause inherited ventricular tachycardia." (PMID 24130701, 2013).
X-linked myotubular myopathy (3 papers, 2013 to 2016). A rare X-linked congenital myopathy characterized by numerous centrally placed nuclei on muscle biopsy and that presents at birth with marked weakness, hypotonia and respiratory failure. "T-tubule disorganization visualized by immunohistochemistry has already been described in X-linked centronuclear myopathy (XLCNM) which is in agreement with the abnormal distribution of DHPRα1 and RyR1." (PMID 24381816, 2013).
Arthritis (2 papers, 2020 to 2024). Inflammation of a joint. "Moreover, increased nNOS has been linked to higher levels of 3-NT modifications on the RyR1 complex skeletal muscle afflicted by arthritis-induced muscle weakness, and thus implying that nNOS is directly involved in adding oxPTM on RyR1." (PMID 33146370, 2020). "We have previously shown that muscle from mice with arthritis have higher levels of nitration markers on the RyR1–DHPR super complex which was accompanied by altered Ca2+ release." (PMID 39499505, 2024).
arthrogryposis multiplex congenita (2 papers, 2017 to 2025). Arthrogryposis multiplex congenita (AMC) is a group of disorders characterized by congenital limb contractures. "The clinical findings of AD RYR1‐related CMs were highly heterogeneous, ranging from mild nonprogressive myopathy occurring in multiple generations of studied families to severe muscle hypotonia with arthrogryposis multiplex congenita and skeletal deformities." (PMID 40525497, 2025).
autosomal recessive centronuclear myopathy (2 papers, 2021 to 2025). Autosomal recessive centronuclear myopathy (AR-CNM) is an inherited neuromuscular disorder defined by numerous centrally placed nuclei on muscle biopsy and clinical features of a congenital myopathy. "RYR1-related autosomal recessive centronuclear myopathy (RYR1-related ARCNM, OMIM#255320) is caused by mutations in the RYR1 gene encoding the ryanodine receptor, which is the main sarcoplasmic reticulum (SR) calcium release channel in skeletal muscle." (PMID 34768808, 2021). "In our experience, patients with STAC3 disorder have been commonly mistaken as having SMA, RYR1-related autosomal recessive centronuclear myopathy, or PWS." (PMID 38824262, 2025).
cognitive deficits (2 papers, 2020 to 2023). "The substitution reverses the inhibitory action of CLIC2 on RyR1 and RyR2, so that the H101Q CLIC2 becomes a strong activator of the ion channels and is associated with seizures, cognitive impairment and learning disabilities." (PMID 38203604, 2023).
congenital heart defects (2 papers, 2021 to 2025). "Though this evidence seems to suggest a possible link between RYR1 variants and conotruncal heart defects, further evidence supporting the link runs short." (PMID 34528764, 2021). "Is congenital heart disease part of the RYR1‐RM phenotype or was this unrelated to the genotype and second to another possibly multifactorial etiology?" (PMID 34528764, 2021). "Additional evidence supporting the possibility of congenital heart disease being part of the RYR1 phenotypic spectrum of disease comes from a large study evaluating 2,871 patients with congenital heart disease using WES." (PMID 34528764, 2021). "Given this historical information, structural congenital heart disease would not be attributed to pathogenic RYR1 variants." (PMID 34528764, 2021). "While clues to the bleeding connection were evident, no previous case reports of congenital heart disease and RYR1‐RM existed in our literature review." (PMID 34528764, 2021).
depression (2 papers, 2021 to 2025). "Some studies have also associated RYR1 protein expression in regulating depression-like behaviors in mouse models." (PMID 40430072, 2025).
epilepsy (2 papers, 2013 to 2023). A brain disorder characterized by episodes of abnormally increased neuronal discharge resulting in transient episodes of sensory or motor neurological dysfunction, or psychic dysfunction. "Specific NO-mediated PTMs are implicated in epilepsy; for example, NO is responsible for type 1 ryanodine receptor (RyR1) S-nitrosylation, inducing Ca2+ release from the endoplasmic reticulum through the Ca2 + release channel, and worsening the disease progression." (PMID 37764469, 2023).
Huntington disease (2 papers, 2015 to 2017). Huntington disease (HD) is a rare neurodegenerative disorder of the central nervous system characterized by unwanted choreatic movements, behavioral and psychiatric disturbances and dementia. "In the present study, we investigated gene expression profiles in the kidneys, and unexpectedly found that 6 SHRSP-specific genes isolated from the rats at 6 weeks of age (Banp, Ephx2, Rbfox1, Rxrg, Ryr1 and Zbtb16) were annotated to ‘Huntington's disease'." (PMID 26165378, 2015). "G-4 genes included 6 genes: Btg3 associated nuclear protein (Banp), Ephx2, retinoid X receptor gamma (Rxrg), Ryr1, RNA-binding protein fox-1 homolog 1 (Rbfox1) and Zbtb16 categorized as ‘hereditary disorder (Huntington's disease)'." (PMID 26165378, 2015).
Hyperkalemia (2 papers, 2021 to 2025). An abnormally increased potassium concentration in the blood. "A potential mechanism of its involvement with the heart might be explained through indirect mechanisms related to secondary effects of RYR1 on metabolic cascades such as hyperthermia, and hyperkalemia." (PMID 34827576, 2021).
hypokalemic periodic paralysis (2 papers, 2015 to 2022). Hypokalemic periodic paralysis (hypoPP) is characterized by episodes of muscle paralysis lasting from a few to 24-48 hours and associated with a fall in blood potassium levels. "Mutations in the CACNA1S, RYR1, SCN4A gene have been reported to be associated with hypokalemic periodic paralysis (HOKPP) in humans." (PMID 35158718, 2022).
Insulin resistance (2 papers, 2019 to 2022). Increased resistance towards insulin, that is, diminished effectiveness of insulin in reducing blood glucose levels. "We have shown that chronic increase in muscle [Ca2+]i caused insulin resistance in two mouse models, RYR1-p.163C, a model of malignant hyperthermia, and db/db, a model of T2D." (PMID 35547584, 2022).
mitochondrial myopathies (2 papers, 2017 to 2025). "Although apoptosis has not been widely reported in RYR1-RM, it is a common process in muscle pathology, including dystrophies, metabolic and mitochondrial myopathies, and inflammatory conditions." (PMID 41301517, 2025).
muscle atrophy (2 papers, 2015 to 2017). The loss of muscle tissue due to inactivity or disease. "In this study, we examined the biological function of CUG-BP1 and altered RyR1 alternative splicing in both human neurogenic muscle atrophy and denervation-induced muscle atrophy mouse model." (PMID 26531141, 2015).
myofibrillar myopathy (2 papers, 2017 to 2021). "Mutations in the RYR1 gene have been reported in mild clinical forms of rigid spine syndrome and in cases similar to myofibrillar myopathy." (PMID 33652732, 2021).
myotonic dystrophy type 1 (2 papers, 2013). Steinert disease, also known as myotonic dystrophy type 1, is a muscle disease characterized by myotonia and by multiorgan damage that combines various degrees of muscle weakness, arrhythmia and/or cardiac conduction disorders, cataract, endocrine damage, sleep disorders and baldness. "Furthermore, RyR1 splicing defects resulting in the expression of the neonatal variants contribute to the pathogenesis of the neuromuscular disease myotonic dystrophy type 1." (PMID 24119341, 2013). "And ASI residues is developmentally regulated: the residues are present in adult ASI(+)RyR1, but absent in the juvenile ASI(−)RyR1 which is over-expressed in adult myotonic dystrophy type 1." (PMID 24098400, 2013).
neuroblastoma (2 papers, 2016 to 2017). Neuroblastoma (NB) is the most common solid, extracranial childhood tumor. "This was also investigated in IMR-32 cells that confirmed the up-regulation of S100A6; IP3R3 and RYR3 but showed no down-regulation of RYR1 in CDDP treated neuroblastoma cells." (PMID 28206967, 2017).
prostate carcinoma (2 papers, 2013 to 2019). A carcinoma that arises from epithelial cells of the prostate gland. "Gene Hsa.11632 (RYR1), together with RYR2 stimulates apoptosis of prostate cancer cells." (PMID 31150453, 2019).
thalassemia (2 papers, 2020 to 2021). An inherited blood disorder characterized by a decreased synthesis of one of the polypeptide chains that form hemoglobin. "Apart from that of the known molecular marker IDH1, we found that the status of cell division cycle 27 (CDC27), podocon (PODN), α-thalassemia/mental retardation syndrome X-linked (ATRX) and ryanodine receptor type 1 (RYR1) was significantly different between the two subgroups (P<0.05)." (PMID 34025640, 2021).
thyroid cancer (2 papers, 2022). "The analysis showed that the gene expression level of JMJD1C, MUC16 and SLA were statistically down-regulated while the gene expression level of PDZD2 and RYR1 were up-regulated in thyroid cancer with respect to normal thyroid tissues." (PMID 35996174, 2022). "For example, RYR1 in cholangiocarcinoma (CHOL) and RYR3 in testicular germ cell tumors (TGCT) only had missense mutations, and RYR2 in CHOL and RYR3 in thyroid carcinoma (THCA) only had silent mutations." (PMID 36167878, 2022). "Since the altered homeostasis of intracellular Ca2+ is correlated to several hallmarks of cancer cells, the study of RYR1 could be interesting to better understand the pathogenesis of thyroid cancer." (PMID 35996174, 2022). "Interestingly, since RYR1 was differentially expressed across all the stages, it is possible that this gene could play a key role in the pathogenesis of thyroid cancer." (PMID 35996174, 2022).
type 2 diabetes (2 papers, 2023). "Combining these new data with existing knowledge of RyRs and IP3Rs suggests that RyR1 might be a potentially useful therapeutic target for treatment during the onset or progression of type 2 diabetes." (PMID 37468098, 2023). "Ultimately, these findings suggest that it might be beneficial to target RyR1 as a potential therapy to alleviate ER stress-mediated beta-cell dysfunction in type 2 diabetes." (PMID 37468098, 2023).
adenoma (1 paper, 2023). A neoplasm arising from the epithelium. "The gene encoding ryanodine receptor 1 (RYR1)—identified as a mutated gene in CRCs from the Thai population compared to the matched normal samples, but not in adenomas —was also predominantly mutated in our CRC group." (PMID 36765865, 2023).
Akinesia (1 paper, 2020). Inability to initiate changes in activity or movement and to perform ordinary volitional movements rapidly and easily. "Regarding RYR1 associated disorders, symptoms are ranging from prenatally diagnosed akinesia, like in case 4, to adult‐onset muscle weakness." (PMID 32779773, 2020).